LEP (leptin)
Diseases named in the same sentence as LEP in open-access papers (continued):
Sharing a sentence is not in itself a finding about the gene and the disease.
breast cancer (continued). "Therefore, the present study aimed to explore the effects of supraphysiological leptin concentrations on proliferation in two breast cancer cell lines." (PMID 24959279, 2014). "Breast cancer cell lines have also been found to express leptin and Ob-R." (PMID 24959279, 2014). "Additionally, increased leptin signaling has also been related to breast cancer growth, angiogenesis and poor outcomes." (PMID 24716804, 2014). "Moreover, a functional Notch-leptin axis is found in mouse carcinogenic-induced and syngeneic breast cancer." (PMID 24716804, 2014). "Leptin signaling can influence pro-angiogenic, inflammatory and mitogenic events in breast cancer." (PMID 24716804, 2014). "Additionally, a significant positive correlation has been obtained between leptin and ObR expressions with breast cancer tissue." (PMID 25866478, 2014). "The differential activation of leptin-mediated signalling pathways across different breast cancer cell lines may further account for the distinctive activation profile of SK1." (PMID 25482303, 2014). "Overall, these studies indicate a biologically relevant cooperation between leptin and estrogen signaling pathways that might sustain the growth of estrogen-dependent breast cancer cells." (PMID 25505738, 2014). "Furthermore, polymorphisms in the LEP and LEPR genes have been associated with several cancer types, such as colon, prostate, and breast cancers." (PMID 26034683, 2014). "Similarly, in human epidermal growth factor (HER)-2 overexpressing SK-BR-3 breast cancer cells, leptin treatment increased proliferation between 5 and 50 ng/ml, but not at 100 ng/ml." (PMID 24959279, 2014). "Notably, our results indicated that leptin specifically correlated with prognosis only among post-menopausal patients with ER+ breast cancer." (PMID 25338520, 2014). "Regarding to the significant roles of leptin in breast carcinogenesis, its inhibition could be considered as a novel strategy for treatment of breast cancer in the future." (PMID 25866478, 2014). "Role of leptin in breast cancer growth and progression: in vitro and in vivo studies." (PMID 25505738, 2014). "BMI and leptin correlated with IL-6 levels in ER+ post-menopausal breast cancer patients." (PMID 25338520, 2014). "Moreover, accumulated evidence from these pre-clinical studies in mice reinforces the idea that leptin-Notch crosstalk plays an important role in breast cancer." (PMID 24716804, 2014). "We have previously unveiled a complex crosstalk between Notch, IL-1 and leptin (NILCO) in breast cancer cell lines, which could be essential for leptin-induced proliferation, inflammation and angiogenesis." (PMID 24716804, 2014). "The enhanced local estrogen production induced by leptin could potentially also shape the breast cancer microenvironment." (PMID 25505738, 2014). "Moreover, it has been reported that leptin enhances aromatase mRNA expression, protein content and its enzymatic activity in breast cancer cells, thereby promoting estradiol synthesis." (PMID 25505738, 2014). "Based on the results, curcumin inhibits the expression and secretion of leptin and it could probably be used as a drug candidate for the breast cancer therapy through the leptin targeting in the future." (PMID 25866478, 2014). "Furthermore, only in ER+ breast cancer patients, we also demonstrated a positive relationship of BMI, leptin, with IL-6." (PMID 25338520, 2014). "Conversely, in MCF-7 breast cancer cells, leptin treatment increased and decreased proliferation." (PMID 24959279, 2014). "Considering important roles of leptin in the breast cancer biology, in this study we investigated the possible variations in the leptin secretion and expression as well as expression of ERs in the T47D breast cancer cell line after its treatment with pure curcumin." (PMID 25866478, 2014). "Leptin could also be involved in the development of drug resistance, metastasis and relapse of breast cancer, which are related to cancer stem cells." (PMID 24716804, 2014).
breast cancer (continued). "Adipokine leptin, produced by adipocytes, fibroblasts, and breast cancer cells, may act in an endocrine, paracrine as well as autocrine manner on breast cancer tissue." (PMID 25505738, 2014). "In these cancers, Notch, leptin and OB-R could further contribute to tumor growth via increased the survival of breast cancer stem cells." (PMID 24716804, 2014). "As a potential explanation, leptin may interact with the HER-2/neu receptor in SK-BR-3 breast cancer cells, which is overexpressed in these cells, resulting in decreased MAPK activity." (PMID 24959279, 2014). "The complex crosstalk between leptin, IL-1 and Notch could differentially drive breast cancer growth and angiogenesis." (PMID 24716804, 2014). "Importantly, we show that SK1 plays a key role in leptin-induced breast cancer cell proliferation, indicating a clear physiological importance of this pathway." (PMID 25482303, 2014). "In a study aiming to potentiate the antitumor effects of cAMP-agonists, leptin induced apoptosis in MDA-MB-231 breast cancer cells when cAMP levels were increased, which resulted in ERK1/2 inactivation and the subsequent inhibition of protein kinase A (PKA) expression." (PMID 24959279, 2014). "In the MCF7 breast cancer cell line, leptin could induce cell proliferation and reduced the efficacy of all breast cancer therapies (tamoxifen, 5-fluorouracil, taxol and vinblastin)." (PMID 23554900, 2013). "NILCO could represent the integration of developmental, pro-inflammatory and pro-angiogenic signals critical for leptin-induced breast cancer cell proliferation/migration, tumor angiogenesis and breast cancer stem cells." (PMID 24202338, 2013). "There are also data showing an anti-apoptotic effect of leptin in breast cancer cell lines." (PMID 22968658, 2013). "We believe that, with further investigation on leptin, new medications could be developed to combat breast cancer and other breast diseases." (PMID 23826274, 2013). "In the subgroup analysis by tumor type, the LEP 2548A (or 19G) allele was significantly associated with risk of prostate cancer (AA vs. AG+GG: OR=1.26, 95%CI=1.05-1.51) but not with cancers of the breasts and colorectal or other specified cancers." (PMID 24146750, 2013). "As such, enhanced estrogen production in the adipose tissue of obese subjects could potentially stimulate an altered ASC phenotype to secrete an abundance of leptin to alter the gene expression profile of breast cancer cells." (PMID 24176089, 2013). "The ER upregulated a number of genes involved in angiogenesis and vasculogenesis and leptin crosstalk to ER could contribute to the development of estrogen-responsive breast cancer and tumor angiogenesis." (PMID 24202338, 2013). "Leptin’s impact on tumor angiogenesis could be a novel target for breast cancer, especially in obese patients." (PMID 24202338, 2013). "Data revealed that breast cancer subjects had significantly higher systolic blood pressure (p = 0.03), glucose (p = 0.01), triglycerides (p = 0.001), leptin (p = 0.044), resistin (p = 0.04), Ang II (p = 0.02), TNF-α (p = 0.045), and CRP (p = 0.04) than controls." (PMID 23374911, 2013). "Women with breast cancer have higher leptin plasma levels and mRNA expression in adipose tissue as compared to healthy subjects, and the blood levels of estradiol increase proportional to those of leptin." (PMID 23819063, 2013). "Additionally, data from immunohistochemical analysis of breast cancer tissue array (n = 67 invasive carcinomas) suggested co-expression of IL-1R tI, leptin/OB-R and VEGF in cancer and stroma cells." (PMID 24202338, 2013). "Leptin was recently added to the list of Notch regulators in breast cancer." (PMID 24202338, 2013). "A few days in the diagnosis, breast cancer subjects had significantly higher systolic blood pressure (p = 0.03), glucose (p = 0.01), triglycerides (p = 0.001), leptin (p = 0.044), resistin (p = 0.04), ANG II (p = 0.02), TNF-α (p = 0.045), and CRP (p = 0.04) than the controls." (PMID 23374911, 2013).
breast cancer (continued). "Leptin may also promote mammary tumor growth through multiple mechanisms such as modulation of the extracellular environment, down-regulation of apoptosis and/or up-regulation of anti-apoptotic genes." (PMID 23826274, 2013). "KM plots demonstrated that women diagnosed with ER+/PR+ breast cancers whose tumor also expressed high levels of leptin (n = 25) demonstrated poorer prognosis with increased mortality rates as compared to ER+/PR+ breast cancers with lower levels of leptin (n = 73; P = 0.038)." (PMID 24176089, 2013). "Furthermore, leptin-induced regulation of VEGF/VEGFR2 in breast cancer also involved the activation of Src and Gbr2/Gab2/STAT3 and their crosstalk to Rho-GTPases." (PMID 24202338, 2013). "Garofalo reported that high leptin level in obese breast cancer patients might contribute to the development of antiestrogen resistance." (PMID 23826274, 2013). "Ishikawa showed that leptin may play a role in the carcinogenesis and metastasis of breast cancer, possibly in an autocrine manner." (PMID 23826274, 2013). "Hence, compressive analyses of leptin concentration (LC) is a basis to recognize these diseases in PW, specifically in breast cancer and ovarian cancer because its morbidity increases during menopause compared with before menopause." (PMID 24023638, 2013). "In this study, we focused on the relationship between leptin level and breast cancer." (PMID 23826274, 2013). "In summary, leptin might play a role in the formation and development of breast carcinoma as well as prognosis." (PMID 23826274, 2013). "As observed previously with macrophage, adenocarcinoma cell lines and human umbilical vein ECs (HUVEC), intratumoral leptin expression may promote COX-2 expression in EO771 mammary tumor cells, and subsequently, cell proliferation." (PMID 23272114, 2012). "In addition, the significantly reduced mammary tumor growth observed in EE mice was related to lower COX-2 expression while a higher COX-2 expression together with increased leptin detection was observed in tumors that had developed in SE mice." (PMID 23272114, 2012). "Furthermore, our published data strongly suggest that leptin is an important factor for breast cancer development." (PMID 21139583, 2011). "Interestingly, leptin upregulation of VEGF/VEGFR-2 in breast cancer was partially mediated by IL-1/IL-1R tI signaling." (PMID 21731759, 2011). "Notch, IL-1 and leptin are known pro-angiogenic inducers in breast cancer." (PMID 21731759, 2011). "Moreover, studies on leptin (ob/ob) and Ob-R (db/db) mutant mice have provided compelling data supporting a role for leptin in breast cancer development." (PMID 21139583, 2011). "In addition, we have shown that leptin increases protein and mRNA levels of all components of the IL-1 system in breast cancer." (PMID 21731759, 2011). "Leptin has previously shown to transactivate ERα and to induce OB-R in breast cancer." (PMID 21731759, 2011). "We hypothesise that the leptin-induced progression of breast cancer could involve the regulation of IL-1 system expression and activation of NF-κB and/or SP1." (PMID 21139583, 2011). "Moreover, leptin upregulation of VEGF/VEGFR-2 expression was highly dependent of a novel unveiled crosstalk between Notch, IL-1 and leptin (NILCO) in breast cancer cells." (PMID 21731759, 2011). "We have previously shown that leptin signaling could give an additional advantage to breast cancer by up-regulating VEGF/VEGFR-2 before hypoxia is manifested." (PMID 21731759, 2011). "We hypothesized that Notch, IL-1 and leptin crosstalk outcome (NILCO) plays an essential role in the regulation of leptin-mediated induction of proliferation/migration and expression of pro-angiogenic molecules in breast cancer." (PMID 21731759, 2011). "Recently, nonsexual hormones leptin and growth hormones have been linked to the development of colon and breast cancers as well as non-Hodgkin's lymphoma in humans." (PMID 20539819, 2010).
breast cancer (continued). "The aim of our study was to analyze the relationships between hypoxia markers HIF-1α, Glut-1, leptin, leptin receptor (ObR) and other breast cancer biomarkers in primary and metastatic breast cancer in patients treated or untreated with preoperative chemotherapy." (PMID 20569445, 2010). "A recent published study by Perera and colleagues has reinforced this idea, showing data supporting leptin promotion of mammary tumor (MT) growth through multiple mechanisms, including regulating the cell cycle, apoptosis, and modulating the extracellular environment." (PMID 19531256, 2009). "This hypothesis deserves further investigation, in particular the possible link between soy, leptin, and breast cancer." (PMID 19348684, 2009). "Recent reports suggest that leptin is overexpressed in various cancer cells and plays a role in the development and/or progression of variety of variety of malignancies including colon, gastric, endometrial and breast cancers." (PMID 19765303, 2009). "Intriguingly, women in the intermediate tertile of leptin had a nonsignificantly reduced risk for breast cancer compared with those in the lowest tertile." (PMID 19223908, 2009). "These contradictory leptin effects on the migration and proliferation, especially of prostate and breast carcinoma cells, might be ascribable to the hormone-sensitivity of the cells." (PMID 20030801, 2009). "Leptin has been reported to induce tumor developmentin breast cancer, suggesting that suppression of leptin secretion mayreduce tumor progression." (PMID 18615198, 2008). "The molecular mechanisms of this link are not clear, but several studies in animal and cellular models suggested that excess body weight could promote breast cancer through increased production of an adipocyte-derived hormone leptin." (PMID 18945363, 2008). "In experimental studies, leptin consistently stimulated human breast epithelial cell lines and breast cancer-derived cell lines resulting in increased DNA synthesis evaluated by thymidine incorporation test and increased cellular growth estimated by cellular density." (PMID 19017403, 2008). "Expression of leptin and ObR in breast cancer tissues was detected by immunohistochemistry (IHC)." (PMID 18945363, 2008). "Tumor markers that are elevated in breast cancer can upregulate leptin production." (PMID 19017403, 2008). "Leptin induced the breast cancer carcinogenesis and invasion." (PMID 21566743, 2008). "In the context of the most aggressive breast cancer, it is important that leptin could crosstalk with HER2 either through ObR, HER1, and JAK2." (PMID 18945363, 2008). "The data obtained in breast cancer cell models prompted us to investigate whether ObR isoforms together with their ligand, leptin, can be coexpressed with HER2 in human breast cancer." (PMID 18945363, 2008). "Also, while this long-term mouse experiment was under way, additional publications further supported that leptin stimulates proliferation and affects signal transduction in breast cancer cell lines." (PMID 18162139, 2007). "PNMT is thought to regulate leptin levels and could be relevant to breast cancer biology via its effect on body weight." (PMID 17117180, 2006). "The relationship between leptin serum level and breast cancer is still controversial." (PMID 16504019, 2006). "Epidemiological studies on leptin and breast cancer have been scarce and inconclusive." (PMID 17010200, 2006). "New data documented that human breast cancer cell lines and breast tumors may express leptin and leptin receptors." (PMID 16504019, 2006). "We have investigated whether genetic variations in LEP and LEPR have implications for susceptibility to and prognosis in breast carcinoma." (PMID 16504019, 2006). "Another small case-control study performed among premenopausal women reported a statistically nonsignificant positive association between serum leptin levels and the risk of carcinoma in situ of the breast." (PMID 17010200, 2006).
breast cancer (continued). "In conclusion, this study suggests that genetic variation in the tandem LEP and its receptor LEPR may be attractive susceptibility markers for breast carcinoma." (PMID 16504019, 2006). "Recent studies have also revealed that leptin decreases the cytotoxicity of NK cells against breast cancer cells by upregulating PPARG coactivator 1 alpha (PGC1α), suggesting that targeting leptin or PGC1α could enhance NK-based immunotherapy against breast cancer." (PMID 40303301, 2025). "Moreover, leptin promotes the proliferation of breast-cancer cells." (PMID 41353220, 2025). "In addition, leptin has been found to promote VM in breast cancer cells." (PMID 40565190, 2025). "Additionally, co-culture of breast cancer cell lines and human femur tissue derived from patients undergoing hip replacement surgery induced the upregulation of IL-1β and leptin and promoted the colonization of cancer cells within the bone marrow adipose tissue." (PMID 39858071, 2025). "Leptin may play a pivotal role in the pathogenesis, development, and metastasis of breast cancer." (PMID 40783771, 2025). "Also, we show that autophagy inhibition reverted the leptin-induced increase in glycolytic ATP production in triple-negative breast cancer cells, indicating that autophagy also supports glycolysis in this breast cancer subtype." (PMID 38228661, 2024). "The results of the current study confirm that 1,25(OH)2D inhibits the migratory potential of breast cancer cells and that this may be due in part to an indirect mechanism—by altering adipocyte release of chemoattractants, such as leptin, adiponectin, IL-6, and IGF-1." (PMID 39339753, 2024). "Thus, AQP1 is involved in leptin-induced VM in breast cancer cells." (PMID 38791252, 2024). "Therefore, VM is a new therapeutic strategy for breast cancer patients, and leptin is a VM inducer that may be an attractive target for breast cancer patients with VM." (PMID 38791252, 2024). "The secreted leptin binds to the leptin receptor (Ob-R) of breast cancer cells and acts as a growth factor, inducing proliferation, survival, angiogenesis, and metastasis of breast cancer cells, thereby promoting the development and progression of breast cancer." (PMID 38791252, 2024). "Thus, this study demonstrates the role of leptin in the VM in breast cancer cells." (PMID 38791252, 2024). "However, breast cancer cells respond differently depending on leptin concentration." (PMID 38228661, 2024). "Thus, AQP1 mediates leptin-induced VM in breast cancer cells." (PMID 38791252, 2024). "Indeed, even slight changes in interstitial leptin concentration can significantly enhance chemoattraction and recruitment of monocytes and macrophages into breast adipose tissue, leading to altered breast cancer migration and metastatic potential in mouse models." (PMID 39439572, 2024). "However, it remains unclear to what extent leptin/Wnt signaling crosstalk supports breast cancer growth by specifically promoting tumor neovascularization, or if other outcomes of leptin/Wnt signaling activation predominate in breast cancer tissue." (PMID 39439572, 2024). "Another possibility is that studies for the association with breast cancer and circulating leptin levels are not identical, and differences in study designs, sample sizes and participant characteristics may matter." (PMID 37274250, 2023). "Furthermore, emerging evidence have proven that elevated expression of leptin and its receptors might potentially contribute to the progression of many tumors, including endometrioid endometrial cancer, breast cancer, and liver cancer." (PMID 37509115, 2023). "Our results demonstrate that acupuncture can effectively alleviate the fatigue symptoms in breast cancer patients after chemotherapy, and the molecular mechanism may be related to the regulation of the Leptin/AMPK signaling pathway by acupuncture, which is consistent with previous studies." (PMID 37542585, 2023).